GPA33 (glycoprotein A33)
Diseases named in the same sentence as GPA33 in open-access papers (continued):
Sharing a sentence is not in itself a finding about the gene and the disease.
osteosarcoma (1 paper, 2020). A usually aggressive malignant bone-forming mesenchymal neoplasm, predominantly affecting adolescents and young adults. "GD2-EATs and HER2-EATs successfully regressed multiple osteosarcoma PDX tumors, leading to significantly improved survival compared to negative controls [no treatment, unarmed T cells, or control EATs (T cells armed with GPA33-BsAb)], (P < 0.0001)." (PMID 33303017, 2020). "GD2-BsAb and HER2-BsAb suppressed osteosarcoma growth compared to negative controls (GPA33-BsAb) (P = 0.0005 for GD2-BsAb and P = 0.10 for HER2-BsAb, respectively)." (PMID 33303017, 2020).
peritoneal disease (1 paper, 2022). "In addition to the presence of peritoneal disease, by the transcriptome analysis of paired samples of neoplastic tissue and normal gastric mucosa, we have identified a group of six differentially expressed genes that predict poor prognosis: ONG, FABP1, LIF, ONECUT2, SFRP2, and GPA33." (PMID 35847866, 2022).
scleroderma (1 paper, 2021). Scleroderma is a rare autoimmune connective tissue disorder characterized by abnormal hardening of the skin and, sometimes, other organs. "We note 38 of the genes found expressed in T cells TADs encompassing the scleroderma associated SNPs were also found to be differentially expressed in Dolcino’s study, including BSG, FCER2, GPA33, MAP2K7, SCAMP2, and TSPAN33." (PMID 33894768, 2021).
tumor (33 papers, 1996 to 2026). "Due to this specificity in tumor cells, GPA33 is an interesting target for α-sarcin-based IMTX in comparison with other tumor-associated antigens." (PMID 41596412, 2026). "GPA33 expression showed consistent intratumoral heterogeneity in CRC with antigen loss at the infiltrative tumor edge." (PMID 39472498, 2025). "In the present study we report high-TI 225Ac-DOTA-PRIT in a preclinical model of CRC targeting two different tumor-associated antigens: GPA33 and HER2." (PMID 40756357, 2025). "However, 17% (2/12) of the samples had less than 20% positively stained tumor cells, suggesting the possibility of immune tumor evasion and/or loss of GPA33 antigen/epitope expression in these samples." (PMID 40521192, 2025). "Low GPA33 expression levels were linked to tumor progression in patients with CRC." (PMID 39472498, 2025). "Importantly, GPA33-loss in tumor cells generally occurred in a stereotypic pattern towards the infiltrative tumor edge." (PMID 39472498, 2025). "This hypothesis is further substantiated by the significant inverse association we observed between GPA33 expression levels and the presence of distant metastases or tumor progression in patient cohorts." (PMID 39472498, 2025). "A key factor that could explain the enhanced potency of HER2 compared to GPA33 likely relates to differences at the cellular level and the contrasting intrinsic biology of the two tumor-associated antigens." (PMID 40756357, 2025). "GPA33 on tumor cells has a function related to the maintenance of the mucosa produced by the gut and to the regulation of the intestinal immune response." (PMID 41596412, 2026). "The uptake of 225Ac at the tumor correlated with antigen expression (antigen expression for GPA33:HER2 is 5:1)." (PMID 40756357, 2025). "We show that treatment of tumor-bearing mice with LGK-974 resulted in nearly all cancer cells expressing GPA33." (PMID 39472498, 2025). "While most recurrent liver tumors and extrahepatic metastases (i.e., metastases beyond the liver) maintained high GPA33 expression post-treatment, a small subset (17%, 2/12) of submitted samples showed less than 20% positively stained tumor cells." (PMID 40521192, 2025). "We observed the strongest mean difference in signaling pathway activity for WNT, which was downregulated in the GPA33-high tumor cell population." (PMID 39472498, 2025). "Peak tumor uptake was achieved rapidly, as a maximum average uptake of 31 ± 12 %ID/g or 11 ± 1 %ID/g was observed at 2 h pi for targeting GPA33 and HER2, respectively." (PMID 40756357, 2025). "Meanwhile, tumor cell expansion, as measured by cell numbers and confluency, was effectively controlled by GPA33-CAR T cells." (PMID 39472498, 2025). "While 98.2% of these cases showed positive membranous staining of tumor cells, we found a substantial heterogeneity of GPA33 expression at the intratumoral cell-to-cell level." (PMID 39472498, 2025). "We identify WNT-active, poorly differentiated cancer cells as a potential tumor cell subpopulation evading GPA33-targeted therapy." (PMID 39472498, 2025). "Untreated xenograft tumors had membranous expression of GPA33 in tumor cell populations in the tumor center that was lost towards the tumor edge." (PMID 39472498, 2025). "A further important aspect of a potential GPA33 CAR T therapy is the role of active WNT signaling in the tumor microenvironment." (PMID 39472498, 2025). "In contrast, GPA33-positive cancer cells were generally positive for E-cadherin, a marker for tumor cell differentiation." (PMID 39472498, 2025). "Conversely, gene expressions previously linked to tumor cell differentiation and favorable outcome, such as SLC26A3, PIGR, CKB and FABP1, were highly expressed in GPA33-high cancer cells." (PMID 39472498, 2025). "In line with this, we demonstrate that inhibition of WNT signaling in vivo induced GPA33 expression in tumor cells at the tumor edge and reduced intratumoral heterogeneity for this antigen." (PMID 39472498, 2025).
tumor (continued). "MGD007, a fragment-based BsAb aimed at redirecting T cells to GPA33-positive tumor cells, displayed the ability to inhibit tumor proliferation at low doses in a xenograft model." (PMID 34922633, 2021). "The impact of variation in tumour antigen (GPA33) expression, tumour size, specimen type (primary vs metastatic), presence of macroscopic necrosis, and tumour vasculature on huA33 uptake were examined." (PMID 24995151, 2014). "Further preclinical and early clinical trials in man are needed to evaluate on-target, off-tumor effects—such as those that may arise from GPA33 expression in normal gut tissue." (PMID 40756357, 2025). "We hypothesized that targeting GPA33, the antigen with the greatest tumor expression and thus the most favorable tumor-absorbed dose, would lead to greater tumor control in comparison to HER2 during head-to-head studies." (PMID 40756357, 2025). "This consistency suggests that primary tumor biopsies may be used to determine patient eligibility for GPA33-targeted therapies aiming at both the primary tumor and its metastatic lesions." (PMID 39472498, 2025). "Furthermore this increase in GPA33 positive tumor cells caused reduced tumor cell heterogeneity of this antigen, resulting in an extension of GPA33 expression towards the tumor edge." (PMID 39472498, 2025). "This suggests that there may be an unidentified resistance mechanism against GPA33 targeted therapy, possibly due to treatment resistant tumor cell subpopulations." (PMID 39472498, 2025). "Finally, SPECT results at 24 h showed superior tumor targeting by [177Lu]Lu-Gemini compared with [177Lu]Lu-ABD for low GPA33-positive LoVo tumors." (PMID 40521192, 2025). "Importantly, all treatments significantly increased the fraction of GPA33-positive tumor cells in this model." (PMID 39472498, 2025). "For anti-GPA33 therapy, a single mouse was still alive at 124 d with a tumor volume of 96.2 mm3." (PMID 40756357, 2025). "The [225Ac]Ac-Pr dosing experiment targeting GPA33 showed that the highest tumor-to-kidney ratios could be achieved at [225Ac]Ac-Pr mass doses between 350 and 700 pmol." (PMID 40756357, 2025). "Considering the slow tumor targeting of large hurA33 and the low affinity of small A33scFv, it is better to develop divalent diabodies, minibodies, or scFv-Fc antibodies against GPA33 as imaging tools." (PMID 26090413, 2015). "Thus, most of the remaining cells from these tumors lost the GPA33 antigen and, presumably, the tumor aggressiveness." (PMID 25883890, 2015). "Strikingly, Gpa33−/− mice develop increased numbers of and larger tumours than WT control mice, suggesting that loss of GPA33 leads to both an increase in the incidence of tumour formation and the rate of tumour growth." (PMID 26035389, 2015). "Colon tumour burden was markedly elevated in Gpa33−/− mice compared to WT mice, as shown by endoscopy of the most distal part of the colon in live animals and by quantitating the number and area of the tumours at the end of the experiment." (PMID 26035389, 2015). "Importantly, all specimens showed that viable tumour cells expressed GPA33 as determined by immunohistochemistry (IHC)." (PMID 24995151, 2014). "Among the upregulated genes, we identified several oncogenes (Ets2, Fyn, Fos, Rab30 and Src), various tumor markers (Cyp1b1, Gpa33, Cd47, Fam129a, st7l, chka, Lgalsbp, Antxr1 and Ly6a) and other genes related to tumor promotion (Cxcl10, Trim25, Grn, Foxc2, Bmp7 and Irs1)." (PMID 23936067, 2013). "The failure of previous anti-GPA33 targeted therapies in clinical trials may have been caused by GPA33-negative stem-like tumor cells or the inclusion of patients with low overall GPA33 expression levels." (PMID 39472498, 2025). "After 66 h of co-culture with GPA33-CAR T cells, we only detected few residual SW1222 tumor cells, while tumor cells challenged with CD19-CAR T cells underwent 3-fold expansion." (PMID 39472498, 2025).
tumor (continued). "Analysis of these xenograft tumors 27-34 days after treatment showed a significant accumulation of human CD3 expressing GPA33-CAR T cells surrounding the tumor margin and partially infiltrating tumor epithelia." (PMID 39472498, 2025). "Biodistribution of [225Ac]Ac-Pr 24 h pi showed efficient targeting of GPA33 in CLR37 PDX, with the tumor uptake being 16 ± 7 %IA/g 24 h pi." (PMID 40756357, 2025). "Given our findings, with a higher frequency of CDX2 than CK20 and especially prevalent GPA33 and CDH17 expression, further studies of this tumor subtype would be of value." (PMID 37349623, 2024). "Single-cycle treatment consisting of α-DOTA-PRIT with either huA33-C825 bispecific anti-tumor/anti-DOTA-hapten antibody (BsAb), anti-HER2-C825 BsAb, or hu3F8-C825 BsAb for targeting GPA33, HER2, or GD2, respectively, was highly effective." (PMID 33052220, 2020). "MGD007 is a gpA33 x CD3 bispecific DART protein designed to recruit/expand host T cells, via their CD3 component, and to mediate tumor cell killing through engagement of glycoprotein A33 (gpA33), a cell surface target on >95% of CRC tumors." (PMID 30400835, 2018). "Immunofluorescence histochemistry revealed that even though membrane GPA33 was expressed in both COLO205 and LS174T tumor grafts at a similar level, the LS174T xenografts were hypervascular." (PMID 26090413, 2015). "We hypothesize that, despite likely differences in antibody-antigen complex trafficking within the cell due to GPA33 or HER2 antigen, tumor cell death can be expected if the radiation dose delivered to the nucleus exceeds a critical threshold." (PMID 40756357, 2025). "Downregulation of WNT activity induced GPA33 expression in vitro and in GPA33-negative tumor cell subpopulations in xenografts." (PMID 39472498, 2025). "Furthermore, testing the impact of tumor cell density on two other CRC cell lines T84 and SW403 showed similar effects on GPA33 levels." (PMID 39472498, 2025). "GPA33-negative cells marked a specific tumor cell subset that is characterized by high WNT activation." (PMID 39472498, 2025). "Kaplan-Meier statistics on the same data that was based on tumor growth endpoints showed a non-significant tendency for longer survival with GPA33-CAR T cell treatments." (PMID 39472498, 2025). "GPA33 is expressed in differentiated tumor cells in the tumor center but is gradually lost towards the tumor margin, with GPA33 negative cells at the interface between tumor and tissue microenvironment." (PMID 39472498, 2025). "In contrast to SW1222, T84 cells form xenografts that have large GPA33 positive tumor cell populations and only few tumor cells at the tumor edge that are negative for this antigen." (PMID 39472498, 2025). "In summary these data suggest that GPA33-CAR T cells recognize their target antigen on xenograft tumors in vivo and may slow tumor growth." (PMID 39472498, 2025). "For single-cycle treatments (37 kBq) of either anti-GPA33 225Ac-DOTA-PRIT or anti-HER2 225Ac-DOTA-PRIT, all treated mice showed complete response (CR; tumor volume ≤10 mm3) at approximately 20 d post-treatment; however, tumor escape was observed for most of the animals." (PMID 40756357, 2025). "Interestingly, RNA expression in tumor tissue was only evident for CEACAM1, MAGEA4, SRC, TPBG, GPA33, and SUB1, with the highest and lowest expression for SRC and MAGEA4, respectively." (PMID 39949781, 2025). "Albeit strong CAR T cell activation in vitro and high GPA33 antigen expression in T84-derived xenografts, we observed only limited effects on tumor growth and low CAR T cell infiltration of the tumor in vivo, which may be related to T cell exhaustion." (PMID 39472498, 2025). "Furthermore, MGA012 enhances MGD007-mediated CTL activity and interferon gamma release upon exposure to gpA33-positive CRC and T cells, while MGD007 anti-tumor activity in preclinical mouse models is enhanced upon combination with anti-PD-1." (PMID 30400835, 2018).
tumor (continued). "Gpa33−/− mice did not exhibit an increase in sporadic CRC incidence or tumour size compared to WT controls." (PMID 26035389, 2015). "Surprisingly, we failed to obtain high-contrast images of mice with GPA33-positive COLO205 tumor grafts after they had been injected with the same amount of CF750-A33scFv-Fc." (PMID 26090413, 2015). "In contrast, Gpa33−/− mice treated with AOM alone showed no increase in sporadic tumour formation, indicating that their increased tumour susceptibility is dependent on inflammatory stimuli." (PMID 26035389, 2015). "GPA33 was expressed in all viable tumour cells, and huA33 uptake was excellent regardless of tumour size and specimen type." (PMID 24995151, 2014). "A subpopulation of GPA33-negative tumor cells was found in 95.0% of CRCs." (PMID 39472498, 2025). "To further characterize tumor cells with and without GPA33 expression, we analyzed a subset of 14 CRC cases using double immunofluorescence and confocal microscopy for key cell state markers of WNT activity (β-catenin), EMT (LAMC2), differentiation (E-cadherin), and proliferation (Ki67)." (PMID 39472498, 2025). "Tumor response was likely limited by a combination of factors including the non-internalizing huA33 BsAb-GPA33 antibody-antigen complex 44 and low [225Ac]Pr specific activity, significantly impacting tumor localization of decay daughters and absolute tumor uptake of 225Ac, respectively." (PMID 33052220, 2020). "After the intravenous injection of mice bearing subcutaneous GPA33-positive LS174T tumor grafts with near-infrared fluorescence probe CF750-labeled A33scFv-Fc (CF750-A33scFv-Fc), high contrast images of the tumor grafts could be kinetically documented within 24 h using an optical imaging system." (PMID 26090413, 2015). "However, injecting the same amount of CF750-A33scFv-Fc did not allow the visualization of the subcutaneous GPA33-negative SMMC 7721 tumor grafts, indicating the high specificity of A33scFv-Fc." (PMID 26090413, 2015). "Both WT and Gpa33−/− mice exhibited activation of the WNT pathway, shown by elevated β-catenin protein and upregulated expression of the WNT target genes, CD44 and Lgr5, in tumours compared to normal epithelium, consistent with CTNNB (encoding β-catenin) being a known AOM target." (PMID 26035389, 2015). "While preclinical application of GPA33-targeting antibodies employing bispecific T-cell engaging antibodies, immunotoxins, and click-mediated radiotherapy showed promising results in tumor models and xenografts, clinical trials did not provide successful response rates." (PMID 39472498, 2025). "Therefore, differences in the effectiveness of HER2 and GPA33 could not be attributed to obvious heterogeneity of uptake within the tumor mass." (PMID 40756357, 2025). "However, GPA33-negative SMMC7721 tumor grafts could not be visualized by injecting the same amount of CF750-A33scFv-Fc." (PMID 26090413, 2015). "Thus, the absence of the GPA33 antigen after treatment with IMTXA33αS would be consistent with the observed anti-angiogenic effect and the decrease in the proliferative potential of the residual tumor mass." (PMID 25883890, 2015). "For the GPA33 (nonspecific) 225Ac-PRIT group, this occurred at 23 d despite weight losses of 9% and 4% from pretreatment baseline (tumor volumes at 16 d, 95.1 and 43.5 mm3, respectively)." (PMID 40473462, 2025). "These interactions establish a paracrine signaling loop near the tumor edge, creating a WNT-enriched niche that likely explains the observed phenotype of GPA33 negative cells in this location." (PMID 39472498, 2025). "Because both COLO205 and LS174T cells were GPA33-positive, these results suggest that CF750-A33scFv-Fc might not be effectively delivered into COLO205 tumor grafts." (PMID 26090413, 2015).